IL1B (interleukin 1 beta)
Diseases named in the same sentence as IL1B in open-access papers (continued):
Sharing a sentence is not in itself a finding about the gene and the disease.
tumor (continued). "They exhibit pro-inflammatory and anti-tumor properties by releasing various types of pro-inflammatory cytokines and chemochines, such as Tumor Necrosis Factor (TNFα), Interleukin-6 (IL-6), Interleukin-1 Beta (IL-1β) and Nitric Oxide Synthase (INOs)." (PMID 32471272, 2020). "Furthermore, some studies reveal that angiotensin-converting enzyme 2 (ACE2) expression is increased after interleukin (IL)-1β treatment, blockade of IL-1β synergized with blockade of PD-1 can inhibit tumor growth." (PMID 32528284, 2020). "Moderate to light IL1β staining occurred fairly uniformly in tumor cell cytoplasm." (PMID 31923221, 2020). "The obtained results for IL1β proved tumor supersession which could correlated with results of BCL2 and VEGF proteins." (PMID 32981013, 2020). "While IL-1β and IL-6 have been linked to the generation of MDSC inside tumor tissues, CX3CL1 and CCL22 have been found to induce the recruitment of MDSCs into the tumor microenvironment in tumor-bearing hosts." (PMID 32632113, 2020). "Transwell assay was employed to investigate the effect of IL-1β on tumor cells invasion." (PMID 32547321, 2020). "This enhanced tumor growth, however, was blocked by IL-1β neutralization or macrophage depletion." (PMID 31649305, 2020). "Mechanistically, IL-1α and IL-1β secreted by melanoma cells increase COX-2, PD-L1, and PD-L2 expression levels in tumor associated fibroblasts which, in turn, suppress the function of tumor-infiltrating T cells." (PMID 32604720, 2020). "In the current study, we demonstrated that IL-1β could promote the colony formation, cell proliferation and tumorigeneicity, which indicating that IL-1β stimulating induced tumor growth both in vitro and in vivo." (PMID 32547321, 2020). "The results for IL1β were similar except that human tumor tissue stained more often than in the hen, which might be explained by differences in the antibody efficacy for hen and human immunohistochemistry." (PMID 31923221, 2020). "Tumor proliferation, the inflammation generated against it via IL-1β secretion or liberation of DAMPs from dying cells, which are potent TLR ligands, might be participating in the process." (PMID 33178579, 2020). "We detected the levels of three key factors in the tumor group of mice: IL-1β, TNF-α and MMP9." (PMID 32796132, 2020). "We observed that, compared to mice bearing tumor tissues collected nude mice injected with Huh7-shCD44 cells subcutaneously, IL1B treatment significantly recovered the damaged tumor growth and metastasis, which were both evidenced by the increasing tumor volumes and rate of lung metastasis." (PMID 33168816, 2020). "Indeed, in vitro studies showed that ASC released by tumor cells induced IL-1β release by macrophages, and CAFs, activated with the supernatant of ASC positive tumor cell-conditioned macrophages, secreted TSLP." (PMID 32117971, 2020). "The chronic low levels of IL-1β produced by the tumor itself may promote an immune-suppressive environment." (PMID 33322216, 2020). "IL-1β then activates neutrophils to dampen CD8-mediated anti-tumor immune response." (PMID 32635472, 2020). "Notably, adding anti-IL6 or anti-IL1β neutralizing antibodies to the co-culture system for the purpose of interrupting the tumor-neuroglia interaction significantly inhibited the development of lung metastasis." (PMID 32308766, 2020). "Furthermore, carcinoma-derived IL-1 (IL-1α and IL-1β) favors a transition from tumor cells into CSCs." (PMID 32635472, 2020). "Moreover, we have shown in our previous studies that IL-1β and IL-6 are up-regulated in NPC cells by LMP1-induced glycolysis or suppression of STING signals, leading to tumor-associated MDSC expansion." (PMID 32632113, 2020). "The result suggested that Hep-2 cells secreted IL-1β in the xenograft tumor microenvironment." (PMID 32577124, 2020). "In addition, patients whose tumors presented IL-1β expression were diagnosed with larger tumor size (p = 0.032) and required a higher RAI cumulative doses (p = 0.004)." (PMID 32139737, 2020).
tumor (continued). "IL-1β produced at the tumor site can induce macrophage chemotaxis." (PMID 32635472, 2020). "Inhibition of AM and neutrophil induced IL-1β and IL-23 led to decreased tumor growth." (PMID 33375062, 2020). "We finally verified whether gAcrp suppresses inflammasomes activation in tumor tissues and found that gAcrp reduced the expression levels of active IL-1β and p20 caspase-1." (PMID 32155890, 2020). "Interestingly, a recent study identified a critical in vivo role for tumor cell-derived IL-1β in inflammatory CAF activation and immune suppression using murine orthotopic models of PDA." (PMID 32329713, 2020). "In particular, IL-1β promotes carcinogenesis, tumor proliferation, and invasion." (PMID 33014808, 2020). "Several cytokines, which can arise from either tumor cells or immunocytes, such as tumor necrosis factor (TNF)-α, interleukin (IL)-1β, IL-6, IL-8, IL-10, and vascular endothelial growth factor (VEGF), have been linked with cancers and can either promote or inhibit tumor development." (PMID 32847533, 2020). "However, when we used chlodronate liposomes to deplete the macrophages, the L-MP-mediated promotion of IL-1β production and tumor growth was blocked, suggesting that IL-1β produced by L-MP-treated macrophages promotes lung tumor development." (PMID 31649305, 2020). "The increased expression of ALDH after IL-1β stimulation might confer more tumor cells with stem cell capability." (PMID 32547321, 2020). "Interleukin-1 beta (IL-1β) drives tumor growth, invasion, and metastasis." (PMID 32802118, 2020). "Furthermore, in vitro studies indicate that tumor cells expressing high levels of IL-1β specifically home to and colonize the bone." (PMID 33339340, 2020). "Furthermore, TAMs are a source of cytokines such as TGF-β1, STI1 (stress inducible protein 1), EGF (epidermal growth factor), IL-6 (Interleukin 6) and IL-1β (Interleukin 1 Beta) that promote growth, migration and mesenchymal transformation of the tumor cells." (PMID 32570988, 2020). "In addition, lncGALM induced interleukin‐1β (IL‐1β) expression that mediates invasive cancer cell extravasation, highlighting its role in multiple‐step metastasis that involves tumor cell migration, adhesion, extravasation, and relocalization in the liver." (PMID 33252861, 2020). "M2 macrophages could promote tumor metastasis by inducing epithelial–mesenchymal transition (EMT) or secreting cytokines such as IL-1β." (PMID 32133283, 2020). "Our study demonstrated that IL-1β could enhance the stemness of tumor cells, indicating that blockade of IL-1β might be an effective strategy to enhance the anti-tumor immunity of CSC-DC." (PMID 32547321, 2020). "Microenvironment, redox balance and osmolarity of cells may influence the release of IL-1β from different tumor types." (PMID 33613529, 2020). "It was previously demonstrated that IL-1β may promote tumor growth and invasion through activation of cancer stem cell self-renewal." (PMID 33613529, 2020). "High levels of cytokines, especially IL-1β and IL-18, were detected in the tumor microenvironment." (PMID 33015196, 2020). "In addition, pro-inflammatory cytokines, including TNF-α, IL-6, and IL-1β, play key roles in regulating inflammation and tumor progression." (PMID 32679895, 2020). "Inflammation-related factors in whole tumor samples were shown to present distinctive expression of pro-inflammatory cytokine as IL-1β and anti-inflammatory cytokine as IL13 (higher and lower, respectively) in cachectic cancer patients and weight stable counterparts." (PMID 33604297, 2020). "Taken together with our findings, these data suggest that the transcriptional activation of both IL1A and IL1B may be functionally relevant within the tumor microenvironment of squamous-subtype PDA tumors." (PMID 32329713, 2020).
tumor (continued). "In PD, increased cytokine levels in response to cellular stress can lead to neuronal cell death whereas in GBM, cytokines like interleukins IL-1β, IL-6, and IL-8 released by the tumor cells, inhibit the immune response and allow the tumor cells to escape the eradication by the immune system." (PMID 32973662, 2020). "To address this, we analyzed cytokine levels in MC38 tumor lysates from tamoxifen-treated Ptpn6fl/flERT2-cre and Ptpn6fl/fl mice at study endpoint and observed increased levels of the proinflammatory, myeloid-derived cytokines IL-1β, and IL-12p70." (PMID 33133093, 2020). "Also, treating WT mice bearing 4T1 tumors with anti-IL-1β followed by anti-PD-1 resulted in complete abrogation of tumor growth." (PMID 32784928, 2020). "Moreover, the ALA-PALE region was characterized by an overexpression, with respect to both ALA+ and ALA−derived GASC, of CCL20, CSF3 and IL1B (magenta box), suggesting the possible importance of these three genes in the infiltrating front of the tumor." (PMID 33066172, 2020). "However, these blockers inhibit both IL-1β and IL-1α, but IL-1α can have tumor promoting or inhibiting functions, and inhibiting this isoform together with IL-1β can have synergistic or antagonist effects, depending on the context." (PMID 32635472, 2020). "Additionally, CXCR6high tumor cells in HCC can secrete cytokines such as IL-1β, IL-6, and IL-8, induce the infiltration of CD66b+ neutrophils, and promote neutrophil-mediated multiple protumor responses." (PMID 32770081, 2020). "Focusing on the functional interaction that occurs between tumor cells and the surrounding stroma, we also determined that IL-1β secreted by hypoxic TNBC cells may promote a feed-forward loop engaging its cognate receptor IL1R1 in breast CAFs." (PMID 32778144, 2020). "IL-1β can be considered as both pro- and anti-tumoral; that is, it promotes anti-tumour responses via its pro-inflammatory nature and its ability to promote Th17 differentiation and neutrophil activation and it is also able to drive pro-tumour responses via tumour invasiveness and immunosuppression." (PMID 32168834, 2020). "In this system, we demonstrated that cell-to-cell contacts between the tumor cells and the stromal cells, as well as soluble mediators, have led to increased production of inflammatory chemokines; this process was further promoted by stimulation of tumor-stroma co-cultures with TNFα and IL-1β." (PMID 32582148, 2020). "IL-1β participated in inflammatory processes, tumor invasiveness and metastasis 13-17." (PMID 32547321, 2020). "IL-1β-induced inflammation increases IL-10 production by MDSCs and activates MDSCs, which are more effective at down-regulating macrophage production of IL-12 as compared with MDSCs isolated from less-inflammatory tumor microenvironments." (PMID 32635472, 2020). "As expected, IOP also enhanced the secretion of cytokines IL-1β and IL-18 in tumor cells." (PMID 33603669, 2020). "Cytokines are a family of soluble factors, classified into growth factors, chemokines, angiogenic factors and interferons and involved in tumor immune-landscape, by exerting pro- (IL-1β, IL-6, IL-8, and macrophage migration inhibitory factor—MIF) and anti-inflammatory (IL-10 and TGF-β) functions." (PMID 32012917, 2020). "Because chronic inflammation may play a greater role during tumor development than acute inflammation, we next investigated the impact of chronic IL-1β exposure on these tumor cells." (PMID 31941995, 2020). "We next investigated the effect of IL-1β on tumor growth in vivo." (PMID 32547321, 2020). "Enhanced IL-1β was positively correlated with advanced tumor stage (P = 0.048)." (PMID 32547321, 2020). "Enhanced tumor progression required IL-1β release from KIT+ MCs localized within the TME." (PMID 32086776, 2020). "It significantly stimulated IL-1β production by the tumor cells." (PMID 31947694, 2020).
tumor (continued). "While some studies reported that 5-FU decreased immunosuppressive MDSC and Treg cell populations consistent with enhancing anti-tumor immunity, 5-FU also was shown to activate the inflammasome in dying MDSCs leading to IL-1β secretion that increased angiogenesis and stimulated tumor growth." (PMID 32575843, 2020). "Furthermore, DHA regulates the crosstalk between autophagy and IFI16/caspase-1 inflammasome, which inhibits IL-1β production in tumor microenvironment." (PMID 32577124, 2020). "As with TNF-α and IL-1β, IL-18 may also exhibit both pro- and anti-tumour activity in CRC, depending on the stage of progression and immune effector cells responsive to IL-18." (PMID 32168834, 2020). "And there was positive correlation between IL-1β concentration and tumor stages (P = 0.012)." (PMID 32547321, 2020). "Approximately 7.98% of the IL-1β-stimulated SCC7 tumor cells were ALDHhigh." (PMID 32547321, 2020). "However, a number of key proinflammatory cytokines, such as IL-1β and IL-6, have been reported to promote tumor progression through the mobilization of MDSCs, the contribution to chronic inflammation and the stimulation of angiogenesis." (PMID 32733461, 2020). "These observed discrepancies make IL-1β a possible target that may need to be taken in consideration, depending on the cancer type and the anti-tumor treatments." (PMID 32635472, 2020). "Further research found that DHA could also reduce the expression of pro-caspase-1 and inhibit the activation of caspase-1 in Hep-2 cells in vitro and IL-1β that was produced in tumor microenvironment in vivo." (PMID 32577124, 2020). "We also analyzed the impact of giving IL-1β and IL-23 on IL-22 levels in tumor tissues." (PMID 32649314, 2020). "Furthermore, caspase-1 was correlated with IL1β (r = 0.74, p = 0.046) in tumor-containing hen ovaries." (PMID 31923221, 2020). "Higher levels of TNF-α and IL-1β are also found in tumor-independent areas of tissue metastases." (PMID 33718121, 2020). "IL-1β is an important molecule involved in the inflammation, carcinogenesis and tumor progression." (PMID 32577124, 2020). "Consequently, Th9 cells generated in the presence of IL-1β exert more marked tumor inhibitory functions." (PMID 32635472, 2020). "In addition, IL-1β-stimulated tumor cells gained enhanced capabilities on wounding healing and invasion capabilities." (PMID 32547321, 2020). "Whether increased IL-1B in the bone environment primes the bone metastatic niche and/or stimulates tumour cells to home to this organ remains to be established." (PMID 31783893, 2019). "Given the tumor-promoting properties of IL-1β, the consequent reduced expression levels IL-1β by U937 cells in the presence of vitamin B6, is suggestive that this decrease may be a contributing factor to the anti-proliferative effects noted by vitamin B6." (PMID 31374832, 2019). "In addition, a plethora of factors that are abundant in infiltrated cells that infiltrate the tumor microenvironment (TANs in particular) such as IL-6, IL-8, IL-1β, and TNFα are also able to induce EMT in GC." (PMID 30616627, 2019). "Blocking IL-2 and IL-15 activities in the context of IL-1β administration completely abrogated the ability of Pmel-1 cells to control tumor growth and shortened the life span of tumor-bearing mice, suggesting a strong dependence of IL-1β enhancement of T cell antitumor function on IL-2 and IL-15." (PMID 31405895, 2019). "Dextran sulfate sodium (DSS) and azoxymethane (AOM) plus DSS mouse models show increases in the incidences of acute and recurrent colitis-associated cancer in mice lacking inflammasome genes, which are correlated with the levels of IL-1β and IL-18 at the tumor site." (PMID 31242947, 2019). "The release of IL-1β by DCs in response to doxorubicin treatment plays an important role in recruiting IL-17 producing γδ T-cells which subsequently recruit anti-tumoral IFN-γ expressing αβ CD8+ T-cells into the tumor microenvironment." (PMID 31379850, 2019).
tumor (continued). "Indeed, we and others have shown that in vitro tumor-conditioned tumor-associated macrophages (TAMs) exhibit a mixed M1/M2 macrophage phenotype, expressing both M2 (CD163 and CD206) and M1 (IL-1β, IL-6, TNF-α, and CCL3) markers." (PMID 30917934, 2019). "The higher relevance of Notch1 than of Notch2 to the tumor-stroma-inflammation networks in TNBC was corroborated by similar findings that were obtained with NOTCH1 vs. NOTCH2 co-expression analyses performed with IL-1β." (PMID 31105691, 2019). "Dendritic cell-derived IL-1β exerts anti-tumor effects by promoting CD8+ T cells to produce IFN-γ." (PMID 31754923, 2019). "Indeed, under the hypoxic or inflamed conditions within the aggressiveness niche, IRISOE TNBC tumor cells secrete high levels of IL-1β, which serve to activate and attract MSCs." (PMID 31014367, 2019). "Here we expand these observations and demonstrate that the NLRP3 inflammasome pathway, which regulates the maturation and secretion of IL-1β is activated in CAFs in response to tissue damage, implicating a mechanism by which CAFs mediate tumour-promoting inflammation." (PMID 31558756, 2019). "Overall, our observations suggest that at the TME of TNBC tumors, which is enriched with TNFα and IL-1β, the two pro-inflammatory cytokines regulate tumor-stroma interactions that occur at the tumor site, and that under these conditions the in vivo aggressiveness of the tumor cells is increased." (PMID 31031757, 2019). "We also monitored the body weight of tumor-bearing mice during the treatment course and found that IL-1β only caused a transient weight loss regardless of the infusion of Pmel-1 cells, and no mortality unrelated to tumor burden was observed." (PMID 31405895, 2019). "Furthermore, Th9IL-4+IL-1β cells promote antitumor immune responses in our experimental tumor-bearing model in vivo, achieving superior outcomes than those from classic Th9IL-4+TGF-β cells." (PMID 30914642, 2019). "Additionally, the production of IL-1β by tumor cells promoted epithelial–mesenchymal transition, invasion, migration, and bone colonization." (PMID 31847214, 2019). "Besides, other studies also showed increased IL-1β expression in murine peritoneal macrophages of tumor mice after treatment with MGO." (PMID 31386629, 2019). "Collectively, the data suggest that extracellular ASC released by tumor cells induces IL-1β secretion in TAMs that in turn activates TSLP by CAFs and that ASC is expressed in a high percentage of primary tumors where its expression correlates with reduced survival in PDAC patients." (PMID 30760333, 2019). "For example, IL-1β is required for the polarisation of IFNγ-producing CD8+ T cells; and is also implicated in the immunostimulatory properties of chemotherapy in the generation of anti-tumour γδT cells." (PMID 30538296, 2019). "IL1B, the second upstream regulator with the high z-score in ADC, encodes IL-1β which is one of the inflammatory cytokines, plays a key role in carcinogenesis and tumour progression." (PMID 31877723, 2019). "Interestingly, neural signals initiated by opsonins initiate a neoplasia inflammatory response in the brain, that quickly signals to local pro-inflammatory cytokines IL1B and TNF throughout the body." (PMID 30987199, 2019). "Reduced ST2 might be related to the immunosuppressive milieu favored by the tumor microenvironment, since in vitro studies have shown that sST2 expression is induced by pro-inflammatory cytokines, such as IL1β and TNFα." (PMID 31281317, 2019). "To investigate whether tumor cell-released ASC could act as alarmin for IL-1β secretion by THP-1 we stimulated the cells with untreated or ASC-depleted or isotype control Ab-depleted viable tumor cell supernatants." (PMID 30760333, 2019). "Petrella and Vincenti elucidated that previously established association between high levels of IL-1β and RCC progression might be explained by the stimulation of tumor cell invasion." (PMID 31861116, 2019).